PRDM1 (PR/SET domain 1)
Diseases named in the same sentence as PRDM1 in open-access papers (continued):
Sharing a sentence is not in itself a finding about the gene and the disease.
cancer (continued). "It gives breakthroughs in modulation of the PRDM1-involved signaling network from the stress sentinel responsible for cancer cell survival and the malignant latency in response to cancer treatment." (PMID 33972671, 2021). "Given that PRDM1 is required for cancer cell survival and inhibits anticancer actions, PRDM1 can be expected to trigger cell growth factor-linked survival signals." (PMID 33972671, 2021). "Mechanistically, PRDM1 facilitated clustering modulation of insulin-like growth factor (IGF) receptor-associated genes, which supported cancer cell growth and stemness-linked features." (PMID 33972671, 2021). "PRDM1 is recognized as a tumor suppressor that inhibits the development of cancer cells, including lymphomas." (PMID 33291744, 2020). "The expression of PRDM1 was found positively correlated with cancer stemness in CHOL, KIRP, TGCT, THYM and UVM." (PMID 33384601, 2020). "The present work illustrated a comprehensive workflow for pan-cancer analysis and thoroughly investigated the role of the PRDM1 in cancers." (PMID 33384601, 2020). "On the other side, there is growing evidences showing that the expression of PRDM1 pose differential prognostic impact across different cancers." (PMID 33384601, 2020). "A comprehensive understanding of the prognostic and immunological impact of PRDM1 among cancer types is essential to develop novel immunotherapies." (PMID 33384601, 2020). "We further calculated the detailed immunocyte compositions of patients in these cancer types through CIBERSORT to explore the key cell type that PRDM1 played a pivotal role." (PMID 33384601, 2020). "The PRDM1 expression was significantly and positively correlated with the stromal, immune scores in both favorable and unfavorable cancers." (PMID 33384601, 2020). "Specifically, the ectopic expression of the transcription factor Aiolos induced anoikis resistance to cancer cells by downregulating PRDM1." (PMID 32290321, 2020). "As there are ample evidence supporting the regulatory role of PRDM1, we analyzed its impact on the abundance of immune infiltrates in cancers that harbor prognostic value." (PMID 33384601, 2020). "The expression of PRDM1 positively correlated with cancer stemness in CHOL, KIRP, TGCT, THYM and UVM." (PMID 33384601, 2020). "While the transcriptional targets of PRDM1 in ENKTL are still under investigation, one study has identified several cancer-associated long non-coding RNAs, such as MIR155HG and TERC, as potential targets of PRDM1." (PMID 30935402, 2019). "Specifically, Prdm1 in group 1 ILCs may be critical in preventing the overactivation of macrophages that can lead to cancer development." (PMID 39133873, 2024). "Given its important role in preserving liver cNK cells and ILC1s functional heterogeneity, enhancing Prdm1 function in human NK cells could potentially be a strategy to promote NK-cell-based immunotherapy for cancer." (PMID 39133873, 2024). "The data also support the essential role of Prdm1 in the cancer surveillance mediated by cNK cells." (PMID 39133873, 2024). "This hypothesis is further supported by the results of a very recently published study showing that genetic knockout of PRDM1 in T-cells enhances persistence and therapeutic responses in cancer models of adoptive immunotherapy." (PMID 36350986, 2022). "And KEGG analysis revealed that PRDM1 may be involved in regulating cell membrane or organelle membrane proteins in cancer." (PMID 35607327, 2022). "In addition to effects on growth promotion, PRDM1 was also involved in cancer cell stemness and subsequent chemoresistance in RIS-aggravated CRC cells in the non-canonical Wnt signaling pathway." (PMID 33972671, 2021). "These beneficial actions were due to cancer stemness-associated cellular transformation and enhanced resistance to the cytotoxicity rather than the simply growth promoting action of PRDM1." (PMID 33972671, 2021).
cancer (continued). "In order words, chronic and frequent ribosomal dysfunction may allow cancer cells to adapt to the cytotoxic environment and survive via PRDM1, all of which would aggravate the cancer treatment as the malignant latency." (PMID 33972671, 2021). "However, the regulatory effects of let-7 and miR-223-3p on PRDM1 have only been studied in various cancer types as by today, and their involvement in RA needs to be elucidated." (PMID 33897713, 2021). "Moreover, CRC spheroids displayed more cancer stemness markers in response to ribosomal dysfunction in PRDM1-IGF-dependent ways." (PMID 33972671, 2021). "Moreover, genetic knockdown of PRDM1 attenuated RIS-driven chemoresistance whereas PRDM1 overexpression improved cancer cell survival, indicating that cellular ribosomal stress mitigates conventional chemotherapeutic actions via PRDM1 protein." (PMID 33972671, 2021). "Ribosome-inactivated CRC cells survived more from chemotherapeutic treatment via PRDM1-IGF-mediated regulation of non-canonical Wnt-linked cancer cell stemness, all of which provided mechanistic evidence of chemoresistance of CRC." (PMID 33972671, 2021). "Moreover, ribosomal dysfunction enhanced CD133 expression in cancer spheroid cells, which was also mediated by PRDM1." (PMID 33972671, 2021). "Besides, correlation of the PRDM1 with cancer prognosis, immune infiltrates, checkpoint markers, cancer stemness and drug response were explored." (PMID 33384601, 2020). "TIMER showed PRDM1 positively correlated with the abundance of CD8+ T cell in the all cancer types with prognostic significance while it also positively correlated with the abundance B cell, CD4+ T cell, Neutrophil, Macrophage and Dendritic cell in all the other cancer types except UVM." (PMID 33384601, 2020). "Our study showed that PRDM1 harbor distinct prognostic values across different cancer types." (PMID 33384601, 2020). "Our findings provide clues on the correlation between the expression of PRDM1 and cancer immunity and suggests that it could be a potential predictive maker of the efficacy of immunotherapy." (PMID 33384601, 2020). "Abnormal PRDM1 expression is also associated with other nonhematopoietic cancer cells, such as glioblastoma malignancies." (PMID 33291744, 2020). "Interestingly, our recent pan-cancer analysis of The Cancer Genome Atlas (TCGA) datasets also confirmed that PRDM1 gene is often genetically altered in DLBCL, with 8.2% mutation frequency." (PMID 32290321, 2020). "No individual correlation between the expression of PRDM1 and the abundance of any of the twenty-two immune cell types could perfectly explain the distinct prognostic value of PRDM1 in these cancers." (PMID 33384601, 2020). "The results showed the prognostic impact of PRDM1 across the different cancer types." (PMID 33384601, 2020). "Thus, PRDM1 deprivation induced cancer metastasis through cell invasion promotion and anoikis resistance through p66Shc transcription decrease." (PMID 32290321, 2020). "Therefore, we conducted a pan‐cancer genomic analysis of PRDM1 across 33 cancer types using large‐scale RNA‐sequencing (RNA‐seq) data from TCGA." (PMID 33384601, 2020). "Inhibiting the PRDM1-dependent signaling could be a novel and promising strategy of immunotherapy in cancers including LGG, PAAD and UVM." (PMID 33384601, 2020). "Knockdown of Gls1 increased the expression of Cdkn1a and Cdkn1b and decreased the expression of some critical oncogenes for cancer cell survival, such as c-Myc, Cdk4, and NfκB, as well as some genes which are essential for MM cell survival, such as Irf4, Prdm1, Csnk1α1, and Rassf5." (PMID 31666930, 2019). "In particular, we predict isoform switches that affect the encoded protein for the cancer drivers CCND3, MYH11, MITF, RALGD5, ABI1, PRDM1 and PPARG, which may have implications for targeted therapy development." (PMID 25578962, 2015).
cancer (continued). "Considering the closest flanking genes of intergenic SNPs, the following are noteworthy and could contribute to the carcinogenic process, as has been reported for other cancer types: PRDM1, ATG5, MYC, EID, RLN1, CD274." (PMID 23626673, 2013). "Notably, the GZMA CD4 T cell subset exhibited elevated expression of genes associated with effector and cytolytic functions in CD4 T cells, including GZMA, GZMH, GZMM, and PRDM1, while also showing moderate expression of anti-cancer-related genes such as IFNG, PRF1, and TNFSF10." (PMID 40959273, 2025). "Moreover, PRDM1 overexpression also activated ERK1/2 signals in cancer cells." (PMID 33972671, 2021). "Among the IGF signal-linked genes identified in the present study, PRDM1 downregulated expression of IGFBP3 and thus the effects of IGFBP3 suppression on the ERK1/2 signal as central downstream signaling kinases of IGF-RAS-linked pathways were assessed in ribosome-inactivated cancer cells." (PMID 33972671, 2021). "However, our results indicate that PRDM1-induced non-canonical Wnt5a was linked to chemoresistance in the ribosome-inactivated cancer cells." (PMID 33972671, 2021). "However, deletion of PRDM1 and TNFAIP3 on chr6 has been linked to cancer." (PMID 32512761, 2020). "Based on previous studies, TBX21 (T-bet), PRDM1, and TOX have been reported to be transcriptionally regulated in neoantigen-specific TILs in cancer." (PMID 39870490, 2025). "PRDM1 and ATG5 are both involved in the immunity and pathogenesis of chronic infections such as CHB and cancers." (PMID 38353395, 2024). "READ is a cancer type with frequent PRDM dysregulations, as PRDM1 upregulation and PRDM6/8/11 downregulation were all observed." (PMID 38540967, 2024). "The H-score levels of the protein expression levels of MECOM and PRDM11 were significantly higher in UCEC tissue, whereas the H-scores of PRDM1 and PRDM12 were weakened or undetectable in cancer tissue." (PMID 39468462, 2024). "Other molecules, including PRDM1 (BLIMP1), NFAT, and IL10, are involved in T-cell activation and contribute to T-cell exhaustion in cancer." (PMID 34305618, 2021). "It is also important that strong and positive correlations between PRDM1 and PD1 were seen in all the unfavorable cancer types while this correlation is only present in SKCM among all cancer types with favorable prognosis." (PMID 33384601, 2020). "It is notable that PRDM1 seemed to positively correlated with TNFRSF14 in LGG and UVM among cancers with unfavorable prognosis, while this correlation seems weak or even negative in all cancers with favorable prognosis." (PMID 33384601, 2020). "Generally, PRDM1 expression positively correlates with the expression of LAG3, CTLA4, PDCD1 (PD-1), CD274 (PD-L1), PDCD1LG2 (PD-L2), TIGIT in the majority of 33 cancer types." (PMID 33384601, 2020). "PRDM1 positively correlated with TNFRSF14 in LGG and UVM among cancers with unfavorable prognosis; this correlation were weak or even negative in cancers with favorable prognosis." (PMID 33384601, 2020). "PRDM1 expression positively correlates with the expression of LAG3, CTLA4, PDCD1 (PD-1), CD274 (PD-L1), PDCD1LG2 (PD-L2), TIGIT in the majority of 33 cancer types." (PMID 33384601, 2020). "Known cancer genes such as COL1A1 or STK11 were affected by duplications and other known genes such as CDKN2A, JAK2, PRDM1, FBXW7, or GOLGA5 were affected by deletions in several tumors of this subcluster." (PMID 32604718, 2020). "Furthermore, PRDM1 and IRF, which exhibit higher activity in CD8+ T cells, induce ferroptosis in cancer cells by inhibiting the transcription of GPX4 and driving the expression of transferrin receptor, respectively, thereby improving the TME." (PMID 40454580, 2025).
cancer (continued). "However, the mRNA expression levels of PRDM1, PRDM2, PRDM8, and PRDM11 were higher in normal and cancer tissues." (PMID 39468462, 2024). "In addition, we also discovered the differential expression of PRDM1 and TK1 in Rb subtypes, which are known epigenetic regulators in other cancers." (PMID 35626705, 2022). "Meanwhile, ex vivo studies of cytotoxic CD4+ T cells from human cancer patients points to variable overexpression of either TBX21 or RUNX3 plus BLIMP-1 (via PRDM1) when compared with non-cytotoxic CD4+ T cells." (PMID 34910940, 2021). "The PRDM1 expression was correlated with TMB and MSI in some cancer types." (PMID 33384601, 2020). "Moreover, both PRDM1 and PRDM5 negatively modulate WNT/β-catenin signaling, a pathway involved in the occurrence of several cancers, including glioma and colorectal cancer." (PMID 30347759, 2018). "Il-6, Il-6ra and Prdm1 were specifically up-regulated in disseminated tumors cells but not in carcinomas, suggesting de novo expression of these genes in the microenvironment of the distant organ." (PMID 23520493, 2013). "The epigenetic gene PR domain zinc finger protein 1 (PRDM1) knockdown in T cells showed an increased chromatin accessibility and promoted the expansion of memory CAR‐T cells, which enhanced T cell durability and improved the efficacy of cancer immunotherapy and improved survival rate." (PMID 38783893, 2024). "Altered expression of PRDM1 has also been investigated in several non-hematopoietic cancer cells." (PMID 32290321, 2020). "This could also be explained by the GSEA results in our study that cancers that PRDM1 harbor unfavorable prognosis identified enriched GO terms of negative regulation of cell activation and regulation of lymphocyte activation that not found in cancers with favorable prognosis." (PMID 33384601, 2020).
blood cancers (1 paper, 2021). "Although PRDM1 is a well-known transcriptional regulator of the blood cancers, its contribution to the solid tumors are little established and controversial." (PMID 33972671, 2021).
inflammation (1 paper, 2025). Aberrant reaction of the microcirculation characterized by movement of fluid and leukocytes from the blood into extravascular tissues. "The repressive function of PRDM1 could attenuate liver inflammation, whereas its activation in circulating immune cells may sustain systemic immune activation." (PMID 41343465, 2025).
PRDM1 also shares sentences with these, for which no sentence is quoted: multiple myeloma (14 papers); Obesity (7); pancreatic cancer (7); acute myeloid leukemia (5); asthma (5); HIV-1 infection (5); Insulin resistance (4); abortion (3); encephalomyelitis (3); endometriosis (3); glioblastoma (3); immune diseases (3); non-small cell lung carcinoma (3); pancreatic ductal adenocarcinoma (3); Sjogren syndrome (3); type 1 diabetes (3); allergic asthma (2); allergic disease (2); autoimmune encephalitis (2); breast tumor (2); common variable immunodeficiency (2); depression (2); embryonal carcinoma (2); graft versus host disease (2); hematological diseases (2); hypophysitis (2); infectious disease (2); kala-azar (2); lymphoproliferative disorders (2); myositis (2).
A further 114 diseases each share a sentence with PRDM1 in 2 papers or fewer.